USP24 (ubiquitin specific peptidase 24)
Diseases named in the same sentence as USP24 in open-access papers (continued):
Sharing a sentence is not in itself a finding about the gene and the disease.
cancer (continued). "Therefore, patients with cancer should be treated with chemotherapeutic drugs and USP24 inhibitors together prior to the emergence of drug resistance." (PMID 33846536, 2021). "The biological role of USP24 in cancer is poorly understood." (PMID 34326684, 2021). "Therefore, the future development of novel inhibitor(s) of USP24 to inhibit cancer malignancy shows potential." (PMID 33257797, 2020). "In this study, we also found that loss of the interaction between USP24 and BRD-containing proteins abolished the effect of USP24 in promoting cancer migratory ability, indicating that USP24-stabilized BRD-containing proteins are important for enhancing cancer malignancy." (PMID 33257797, 2020). "Based on our study, targeting USP24 to inhibit the levels of BRD-containing proteins may inhibit cancer progression." (PMID 33257797, 2020). "Nevertheless, the role of USP24 in cancer is far from clear." (PMID 30911287, 2019). "In addition, IL-8 treatment increased cancer malignancy, indicating that not only IL-6 but also other factors regulated by USP24 modulate cancer malignancy." (PMID 30266897, 2018). "USP24 has previously been reported to be involved in cancer progression." (PMID 30266897, 2018). "Here, we provide direct evidence to support that USP24 promotes IL-6 expression, which might be beneficial for cancer therapy." (PMID 30266897, 2018). "We have previously demonstrated that USP24 is involved in cancer progression." (PMID 30266897, 2018). "Therefore, our in vivo data suggested that USP24 regulated IL-6 expression not only affect the intravasation but also the extravasation of cancer cells." (PMID 30266897, 2018). "Thus, USP24 may be not only important inside cancer cells but also critical in other cells around cancer cells." (PMID 38491202, 2024). "Notably, NCI677397 resulted in redox imbalance because it destabilized the GPX4 and DHFR proteins, which might be the substrates of USP24, producing excessive levels of oxidized lipids that drove cancer cells toward ferroptosis." (PMID 38140768, 2024). "Therefore, we studied the role of USP24 in DDR activity during cancer progression." (PMID 33846536, 2021). "Thus, the role of USP24 in cancer needs to be further elucidated." (PMID 34326684, 2021). "Furthermore, we uncovered the mechanisms controlling USP24 regulation during cancer progression." (PMID 27991932, 2017). "Moreover, cdc20 could also interact with USP24 when these residues were phosphorylated, implying that the decrease in USP24 during mitosis might be important for cell cycle progression and cancer cell proliferation." (PMID 27991932, 2017). "Recently, we found that the USP24 inhibitor NCI677397 induced ferroptosis, a type of programmed cell death, in drug‐resistant cancer cells by increasing lipid reactive oxygen species (ROS) levels." (PMID 38140768, 2024). "Taken together, the data revealed that NCI677397 targeting USP24 function as a novel ferroptosis inducer (FIN), which was consistent with recent reports describing it as a novel treatment for reversing cancer cell drug resistance." (PMID 38140768, 2024). "Our previous studies identified a specific USP24 inhibitor, NCI677397, which can inhibit the drug resistance of cancer acquired by Taxol treatment." (PMID 38491202, 2024). "For example, USP24 positively regulates drug resistance partially by stabilizing ABC transporters, including ABCB1, ABCG1, and ABCC1, to pump out drugs from cancer cells." (PMID 36694209, 2023). "USP24 increases the levels of ABC transporters ABCB1, ABCG2, and ezrin to enhance the pumping of taxol from cancer cells." (PMID 36694209, 2023). "All the results show that USP24 stabilizes ABC transporters and increases cancer stemness characteristics to induce drug resistance." (PMID 33846536, 2021). "The other cancer cell lines, Hone-1 and HCT116 cells, were also used to study the role of USP24 in CPT- and oxaliplatin-induced drug resistance." (PMID 33846536, 2021).
cancer (continued). "In this study, we found that USP24 and BRG1 regulate each other and that this regulation is important for cancer metastasis." (PMID 33257797, 2020). "In this study, we found that USP24 and BRG1 regulate each other and that this regulation is beneficial for cancer progression." (PMID 33257797, 2020). "To address the importance of the interaction between USP24 and BRD-containing proteins in cancer progression, we needed to abolish the interaction and study the effects on cancer progression." (PMID 33257797, 2020). "This study shows that USP24 mediates p300, NF-κB, DNMT1, and β-TrCP to regulate IL-6 expression, thus affecting cancer metastasis." (PMID 30266897, 2018). "This study provides important findings for USP24-mediated protein turnover including p300, Bax, E2F4 and securing to regulate apoptosis and proliferation of cancer cells, respectively, which is crucial for cancer tumorigenesis." (PMID 27991932, 2017). "In addition, our recent study showed that USP24 stabilized ABCG2 and P‐gp to promote cancer cell drug resistance, implying that USP24 recognizes specific sequences or structures in ABC transporters, especially G family." (PMID 38140768, 2024). "In this study, we screened a novel-specific USP24 inhibitor, NCI677397, and found that this inhibitor can inhibit ABC transporters and genomic instability and thereby prevents drug resistance to chemotherapy in different cancer types." (PMID 33846536, 2021). "A novel, USP24-specific inhibitor, NCI677397, could stabilize the genome, reduce cancer stemness characteristics, and increase the concentration of a drug inside cells to block the emergence of drug resistance." (PMID 33846536, 2021). "In addition, the knockdown of USP24 increased the colony number and decreased the levels of sub-G1 population in CPT-treated cancer cells, which suggests that USP24 increases the cytotoxicity of CPT and indicates that USP24 inhibits the DDR." (PMID 33846536, 2021). "Regarding the regulation of BRD-containing proteins in cancer progression, in this study, we not only found that most BRD-containing proteins are substrates of USP24 but also elucidated the interaction motif of USP24 and the residues that are ubiquitinated in the BRD, Lys391/Lys400." (PMID 33257797, 2020). "USP24-stabilized BRD-containing proteins may also be involved in genomic stability and thus contribute to heterogeneity during cancer progression." (PMID 33257797, 2020). "In this study, we observed that USP24 increased DNMT1 degradation in cancer cells, but not in M2 macrophages, leading to decreased DNA methylation." (PMID 30266897, 2018). "Additionally, in this study, targeting USP24 showed consistent effect on lipogenesis in primary hepatocytes and in vivo but not in cancer cell lines, HCC cells, and Huh7 cells." (PMID 40448065, 2025). "Herein we found a positive correlation between targeting USP24-mediated LC3-II signaling and the cytotoxicity of Taxol in drug resistance, implying that targeting USP24-induced autophagy might be important for inhibiting drug resistance during cancer therapy." (PMID 38491202, 2024). "After USP24 knockdown, the levels of P-gp, ABCG2, and ezrin were decreased, which indicated that USP24 as a deubiquitinating enzyme may stabilize P-gp, ABCG2, and ezrin to enhance the ability of pumping out of a drug from cancer cells." (PMID 33846536, 2021). "In conclusion, the USP24 level was decreased during the early stage of cancer and the mitotic stage of the cell cycle to regulate its substrates p300, Bax, E2F4 and securin, resulting in decreased cell apoptosis and increased cell cycle progression and, thus, cancer formation." (PMID 27991932, 2017).
cancer (continued). "The data indicated that there was a high relevance between the USP24 level and the substrates identified in this study, suggesting that USP24 might regulate p300, Bax, E2F4 and securin levels to regulate apoptosis and cell cycle progression, resulting in cancer formation." (PMID 27991932, 2017). "In addition, we found that USP24 and BRG1 could regulate each other through regulating the protein stability and the transcriptional activity, respectively, of the other, suggesting that the levels of USP24 and BRG1 are regulated to form a positive feedback loop in cancer progression." (PMID 33257797, 2020).
hematological malignancies (2 papers, 2020 to 2024). "Even though certain reports suggest an indirect role of USP24 in certain hematological malignancies, the function of USP24 in disease prognosis remains unclear." (PMID 32354135, 2020).
neurodegenerative disease (2 papers, 2024 to 2025). A disorder of the central nervous system characterized by gradual and progressive loss of neural tissue and neurologic function. "Knockdown of USP24 can improve neurite extension or maintenance in aged iPSC-derived dopaminergic neurons, implying that USP24-i-101 targeting USP24 may be effective in inhibiting neurodegenerative diseases." (PMID 40448065, 2025).
infection (1 paper, 2025). The state of being infected such as from the introduction of a foreign agent such as serum, vaccine, antigenic substance or organism. "Additionally, EV-A71 exploits post-translational modification, infection-induced ubiquitin-specific protease 24 (USP24) reduces K63-linked ubiquitination of TBK1, crippling its ability to activate IRF3." (PMID 40822588, 2025).
USP24 also shares sentences with these, for which no sentence is quoted: lung adenocarcinoma (3 papers); autism (2); metabolic disorders (2); T-cell acute lymphoblastic leukemia (2); adenocarcinoma (1); alcoholic liver diseases (1); bone cancer (1); cardiovascular disease (1); colorectal cancer (1); dermatomyositis (1); dyslipidemia (1); hyperinsulinism (1); liver (1); liver cirrhosis (1); lymphoma (1); multiple myeloma (1); myeloid leukemia (1); myositis (1); non-small cell lung carcinoma (1); T-cell lymphoma (1); triple-negative breast carcinoma (1).